CD44 (CD44 molecule (IN blood group))
Diseases named in the same sentence as CD44 in open-access papers (continued):
Sharing a sentence is not in itself a finding about the gene and the disease.
head and neck squamous cell carcinoma (continued). "CD44 has been shown to play an important role in resistance to radiation and chemotherapy and may play a role in tumor recurrence of head and neck squamous cell carcinomas." (PMID 26449187, 2015). "Bourguignon and colleagues showed in head and neck squamous cell carcinoma (HNSCC) that miR-21 is up-regulated through the binding of hyaluronic acid to its receptor CD44 and promotion of Nanog-Stat 3 complex formation which allow transcriptional activation and expression of this miRNA." (PMID 22949815, 2012). "In head and neck squamous cell carcinoma (HNSCC) CSCs mouse models, targeting CD44 was shown to inhibit PI3K–4EBP1–SOX2 signaling and tumor growth and decrease the number of CSCs." (PMID 38783892, 2024). "Head and neck squamous cell carcinoma (HNSCC) is the most common type of head and neck cancer, and has been revealed as the second-highest expression of CD44 in cancers." (PMID 37504249, 2023). "The CD44 expression was examined by immunohistochemistry (IHC) in 90 samples of head and neck squamous cell carcinoma (HNSCC) confirmed patients." (PMID 35274800, 2022). "A preclinical model in head and neck squamous cell carcinoma (HNSCC) demonstrated that CD44+ cells have significantly increased PD-L1 expression, both constitutive and inducible, in comparison with their CD44- counterparts." (PMID 34065396, 2021). "CD44 is a marker for CSCs and has proven to be a reliable indicator for detecting head and neck squamous cell carcinoma (HNSCC), and it can be measured simply and inexpensively." (PMID 33530399, 2021). "In a subsequent study, the same group demonstrated that the number of CD44+ cells increased with neoadjuvant chemotherapy in head and neck squamous cell carcinoma (HNSCC) patients." (PMID 26682001, 2016). "Patient samples of head and neck squamous cell carcinoma (HNSCC), for example, contain a heterogeneous population of cancer cells and the small subpopulation CD44+ contained most of the CSCs, evidenced by its tumorigenic potential in immunodeficient mice." (PMID 24775603, 2014). "Previous studies have identified CD44+ cells as cancer stem cells in head and neck squamous cell carcinoma (HNSCC)." (PMID 24612587, 2014). "Recently, the standard form of CD44 (CD44s) was shown to be part of the signature of cancer stem cells (CSCs) in colon, breast, and in head and neck squamous cell carcinomas (HNSCC)." (PMID 18852874, 2008). "CD44 is a transmembrane glycoprotein involved in cell survival, motility, and differentiation as a CSC marker in head and neck squamous cell carcinomas." (PMID 40371051, 2025). "In the head and neck squamous cell carcinoma, treatment with the NLRP3 inhibitor MCC950 decreased sphere and colony formation as well as cancer stem cell marker BMI1, ALDH1, and CD44 expression." (PMID 38904007, 2024). "Examination of the TCGA database unveiled positive correlations between PA28γ expression and both CD44 and CXCR4 expression in the head and neck squamous cell carcinoma (HNSCC) cohort." (PMID 38721005, 2024). "In head and neck squamous cell carcinoma (HNSCC), the CD44-high CSCs from HNSCC exhibited elevated migration, invasiveness, and stemness and could form metastatic foci in the lungs of immunodeficient mice." (PMID 37176118, 2023). "In head and neck squamous cell carcinoma (HNSCC), BMI1 is highly expressed in CD44+ cells that exhibit CSC features of self-renewal, differentiation, and chemoresistance." (PMID 35455671, 2022). "However, the salivary CD44 appears to be a surrogate marker in detection of head and neck squamous cell carcinoma (HNSCC)." (PMID 34858437, 2021). "Wang showed that HA mediated the formation of a complex including CD44 and the epidermal growth factor receptor (EGFR) played major roles in chemoresistance in head and neck squamous cell carcinoma (HNSCC)." (PMID 35154001, 2021). "In head and neck squamous cell carcinoma (HNSCC), p75NTR is considered to be a more specific marker of CSCs than CD44." (PMID 33392191, 2020).
head and neck squamous cell carcinoma (continued). "Importantly, in head and neck squamous cell carcinoma (HNSCC), CD44+ CSCs express higher CD133 levels than CD44- cells." (PMID 31579438, 2019). "CD44, CD133, BMI1 and ALDH are considered frontline markers for detection of CSCs in OSCC, and other head and neck squamous cell carcinomas (HNSCCs)." (PMID 30002682, 2018). "Similar to CD24, previous studies have identified CD44, BMI1 and ALDH1 as putative markers for CSC in head and neck squamous cell carcinomas." (PMID 24612587, 2014). "Finally, in an independent microarray co-culture dataset (GSE178153/GSE178154), patient-derived head and neck squamous cell carcinoma (HNSCC) cell lines from LNM-positive tumors showed significantly higher CD44 expression than those from LNM-negative tumors (P = 0.04)." (PMID 40906645, 2025). "In order to investigate the effect of hsa-miR-6510-3p micro RNA on the stem cell phenotype of cancer cells, cytometric analysis of the expression of CD44 and CD133 - surface antigens considered as markers of the stemness phenotype in head and neck squamous cell carcinoma was performed." (PMID 39966442, 2025). "In the head and neck squamous cell carcinoma cell lines HN-8, HN-30 and HSC-3, apigenin significantly downregulated the stem cell markers of CD44, NANOG, and CD105, and abolished the hypoxia-induced increase in CD44(+) cells, CD105(+) cells and STRO-1(+) cells." (PMID 29034071, 2017). "It has been reported that cells expressing CD44 and aldehyde dehydrogenase (ALDH) activity in head and neck squamous cell carcinoma (HNSCC) exhibit cancer stem cell (CSC)-like properties." (PMID 40394426, 2025). "Mechanistically, it has been shown that HA mediates the formation of a complex including CD44 and the epidermal growth factor receptor (EGFR), which plays major roles in chemoresistance in head and neck squamous cell carcinoma (HNSCC)." (PMID 37958796, 2023). "In head and neck squamous cell carcinoma (HNSCC), however, CSC-enriched populations have been isolated using CD24, CD44, CD133, ALDH1, or CD271 as sorting markers, suggesting that a single common CSC sorting marker may not exist even within identical types of tumor." (PMID 26483189, 2015). "Notch1 also appears to critically regulate stemness in head and neck squamous cell carcinoma (HNSCC) cells, as constitutive activation of NICD in HNSCC cells promotes self-renewal by enhancing tumorsphere formation and upregulating stemness markers such as OCT4, SOX2, and CD44." (PMID 36118530, 2022). "In the case of head and neck squamous cell carcinoma (HNSCC) cells, a comparative analysis of CD44+ cells (indicator of stemness) and control CD44(−) cells revealed that Nanog or ERK1/2 was highly expressed in CD44+ cells." (PMID 36497144, 2022). "Although head and neck squamous cell carcinoma (HNSCC) has a good outcome with surgical intervention, a stem-like chemoresistant cell population that is able to drive relapse has also been identified in HNSCC using CSC cell surface markers such as CD44." (PMID 33530455, 2021). "CD44, an extracellular matrix (ECM) receptor, has been described as a cancer stem cell marker in multiple cancers, including head and neck squamous cell carcinoma (HNSCC)." (PMID 24403253, 2013). "In addition, the surface glycoprotein CD44 and oncogene BMI1 have been identified as key markers of the CSC subpopulation in breast cancer and head and neck squamous cell carcinoma (HNSCC)." (PMID 23300583, 2012).
triple-negative breast carcinoma (102 papers, 2011 to 2025). An invasive breast carcinoma which is negative for expression of estrogen receptor (ER), progesterone receptor (PR), and human epidermal growth factor receptor 2 (HER2). "Based on overexpression and knockdown experiments, it has been shown that TDP43 promotes variant exons inclusion in CD44 mRNA, especially exons v8, v9, and v10, in triple-negative breast cancer cell lines MDA-MB-231 and HCC 1806." (PMID 38106992, 2023). "CD44 has been associated with migration and metastasis, being upregulated in the triple-negative breast cancer subtype." (PMID 32545405, 2020). "The hyaluronan receptor, CD44, is implicated in cancer cell growth and proliferation, and is induced by hypoxia in triple-negative breast cancer." (PMID 26316122, 2015). "Recent studies demonstrated that hypoxia regulates specific variants (i.e. v6 and v7/8) of CD44 through HIF-1α in triple-negative breast cancer cells." (PMID 24586375, 2014). "The schematic diagram illustrates HA-CQDs facilitating ferroptosis-based CD44 targeted anticancer activity in triple-negative breast cancer cells." (PMID 40363642, 2025). "In this study, we synthesized HA-CQDs to enhance CD44-mediated ligand–receptor interactions targeting triple-negative breast cancer (TNBC)." (PMID 40363642, 2025). "HA was grafted onto metformin-loaded GO nanoparticles as a CD44-targeted anti-cancer therapy for triple-negative breast cancer, which exhibited anti-cancer efficacy at a much lower dosage as compared with metformin alone." (PMID 38256139, 2024). "In the triple-negative breast cancer cell lines HCC1806 and MDA-MB-231, SRSF3 has been identified as a positive regulator of variant exon inclusion in CD44 pre-mRNA, especially exons v8, v9, and v10." (PMID 38106992, 2023). "CD81 interacts with CD44 on the membrane and promotes mammosphere formation of triple negative breast cancer (TNBC) cells." (PMID 36193887, 2022). "Despite CD44 is a good marker for triple-negative breast cancer, it is also highly expressed in other normal tissues, such as human breast epithelium." (PMID 36304896, 2022). "HA metabolism was further discovered by the CRISPR/Cas9-mediated knockout of HYAL1 and the shRNA-mediated down-regulation of HA-receptor CD44 in the brain-seeking triple-negative breast cancer (TNBC) cell line MDA-MB-231-BR." (PMID 36291142, 2022). "Studies have shown that MORC2 promotes cell growth and metastasis in human cholangiocarcinoma and is negatively regulated by miR-186-5p, the MORC2-mutant M276I promotes metastasis of triple-negative breast cancer by regulating CD44 splicing." (PMID 36234785, 2022). "The aim of the study was to analyse the effect of a novel thieno[2,3-b]pyridine, compound 1, in MDA-MB-231 triple-negative breast cancer cells (TNBCs) upon CD15s and CD44 expression in different cell subpopulations using flow cytometry." (PMID 34206154, 2021). "The results showed that targeted liposomes had a better targeting ability for triple-negative breast cancer highly expressing CD44." (PMID 34011362, 2021). "Short-term Olaparib treatment has also been previously demonstrated to induce cancer cell invasion and enrich PD-L1 and CD44+CD24– stemness marker levels in triple-negative breast cancer (TNBC) cell lines." (PMID 34956861, 2021). "A previous study has revealed that CD44 was identified as a key positive regulator of PD-L1 expression in triple-negative breast cancer and non-small cell lung cancer." (PMID 34249910, 2021). "Its receptor, CD44, is overexpressed in various tumour cells, including human triple negative breast cancer MDA-MB-231 cells, and is involved in tumour invasion and metastasis." (PMID 33632232, 2021). "In triple negative breast cancer patients, CD44 promotes the transcription of PD-L1, an immune checkpoint, through its cleaved intracytoplasmic domain (ICD)." (PMID 33352739, 2020).
triple-negative breast carcinoma (continued). "The significance of direct interactions of GRP78 (and HSP90α) with PRDM14 for the maintenance of CSC-like populations of CD24(−)/CD44(+) cells and drug-resistant SP cells has been demonstrated in a model of triple-negative breast cancer." (PMID 32268506, 2020). "In the current studies, we demonstrate that triple negative breast cancer cells synthesize and fragment HA and express CD44 on the cell surface." (PMID 32455980, 2020). "Compared with free curcumin, the drug-loaded micelles can significantly reduce the number of CD44+/CD133+ cancer stem cells in triple-negative breast cancer mice model." (PMID 31632958, 2019). "Pyrosequencing analysis suggests DNA methylation changes in a variety of genes regions including CD44 in triple negative breast cancer." (PMID 29747682, 2018). "Activation of epidermal growth factor receptor (EGFR) promoted the CSC phenotype with CD44+/CD24-expression, associated with invasiveness in triple-negative breast cancers." (PMID 29747682, 2018). "Here we used the biomarker combination of ALDH and CD24/CD44 to sort four populations isolated from triple-negative breast cancer (TNBC) patient-derived xenografts, and performed whole-transcriptome sequencing on each population." (PMID 29471829, 2018). "The reduced OCT4 and CD44 expression confirmed our findings that LDR is capable of diminishing CSC-like population in MDA-MB231 triple-negative breast cancer cells." (PMID 28240233, 2017). "Triple-negative breast cancer (TNBC) is an aggressive tumor subtype with an enriched CD44+/CD24- stem-like population." (PMID 26528725, 2015). "After in vivo examination, the classic “stem-like” phenotype of CD44+CD24−/low was applied to determine the effects of ISL on the MDA-MB-231 triple-negative breast cancer cell line and the MCF-7 luminal cancer cell line." (PMID 25918249, 2015). "In conclusion, we demonstrated the inhibitory effects of CDDO-Im on triple-negative breast cancer with a potential to target cancer stem cell subpopulation, as evidenced by inhibition of CD44+/CD24−/low/EpCAM+ cells and tumorsphere formation." (PMID 25229616, 2014). "The authors used a triple-negative breast cancer cell line with a known bi-lineage phenotype to isolate single cells containing high levels of CD44 that exhibited mesenchymal/basal B and luminal/basal A features, respectively." (PMID 24637461, 2014). "We found that the proportion of CD44+CD24− Nestinhigh CSC (57.45 ± 18.27%) were significantly higher than that of CD44+CD24− Nestinlow CSC (42.55 ± 16.4) in the 12 specimens isolated from patients with triple-negative breast cancer (P <0.05)." (PMID 25056574, 2014). "Here, we further analyzed the role of NF-κB in regulating CD44 expression in triple negative breast cancer cells, MDA-MB-231 and SUM159." (PMID 25184276, 2014). "We isolated CD44+CD24− CSC from 26 triple-negative breast cancer tissues to generate Nestin-overexpressing (Nestin+), Nestin-silencing (Nestin-si), and control (Nestin-c) CSC." (PMID 25056574, 2014). "Equally important, our study showed a modest level of CD44 repression by NF-κB is sufficient to significantly reduce the cell proliferation and invasiveness of the triple negative breast cancer cells." (PMID 25184276, 2014). "The nine normal adjacent breast specimens from patients with triple-negative breast cancer, which were all positive for CD44+CD49f+CD133/2+ stem cell staining, also all exhibited high tumorigenic signature patterns." (PMID 24008095, 2013). "However, only one study found that MORC2 mutant M276I regulated hnRNPM-mediated CD44 splicing switch to promote invasion and metastasis in triple-negative breast cancer cells." (PMID 39048555, 2024). "CD44 knockdown in brain seeking triple negative breast cancer cell line (MDA-MB-231-BR) reduced the pericellular HA coat on cancer cells, and consequently, their adhesion and invasion through the BE, suggesting the interaction between HA and CD44 as a potential therapeutic target of BM." (PMID 37190188, 2023).
triple-negative breast carcinoma (continued). "The intracytoplasmic region (ICD) of CD44 cleavage can regulate PD-L1 expression by binding to the coherence site of the PD-L1 gene’s promoter region.Therefore, CD44 is a potential target for inhibiting PD-L1 function in triple-negative breast cancer." (PMID 36964570, 2023). "Meanwhile, MUCIN 1 (MUC1) could bind to the CD44 variant to enhance the stability of SLC7A11, thereby inhibiting erastin-induced ferroptosis in triple-negative breast cancer cells." (PMID 35795552, 2022). "Interestingly, a recent study suggested that soluble CD44 released by triple-negative breast cancer cells promotes tumor progression by triggering macrophage IL-1β production." (PMID 35631400, 2022). "Using protein structure modeling and interface prediction-guided mutagenesis, we demonstrate that membrane CD81 interacts with CD44 through their extracellular regions in promoting tumor cell cluster formation and lung metastasis of triple negative breast cancer (TNBC) in human and mouse models." (PMID 36193887, 2022). "Therefore, through the surface modification of liposomes, the side effects of the drugs can be reduced by targeting triple-negative breast cancer through CD44." (PMID 34011362, 2021). "The results of CD44/CD24 staining in two of the triple-negative breast cancer cell lines tested (MCF10AT and MCF10CA1α) indicated an overall increase in mesenchymal-like CSC population after treatment with Efavirenz, opposite to the results obtained for epithelial-like CSCs." (PMID 34944852, 2021). "Additionally, the CD44 gene in breast CSCs and CD44 gene hypomethylation was correlated with aggressive features of triple-negative breast cancer." (PMID 34944493, 2021). "Previous studies have shown that CD44+/CD24- breast CSCs may be a dominant factor for the relapse of triple negative breast cancer (TNBC), due to their potent self-renewal and differentiation capacities." (PMID 34318746, 2021). "Although further investigation is needed, the disruption of HA-binding and subsequent signaling through CD44 may be an exciting new approach for the treatment of triple negative breast cancer." (PMID 32455980, 2020). "Interestingly, MYC was upregulated in ALDH1-enriched mammosphere cells from cell lines and triple-negative breast cancers; this was seen also in CD44-expressing cells." (PMID 31661927, 2019). "However, other study has indicated that adjacent breast specimens from triple-negative breast cancer, which were all positive for CD44+CD49fCD13372+ stem cell staining, also exhibited high tumorigenic signature patterns." (PMID 26431176, 2015). "Interestingly, inhibition of Cdk2 kinase activity selectively targets and restores the chemosensitivity of SUM149PT in a CD44+/CD24-/Low stem-like subpopulation of triple-negative breast cancer cells." (PMID 25605243, 2015). "Moreover, the CD44+/CD24−/low cells are more abundant in triple-negative breast cancer than in other subtypes, suggesting that the cancer stem cells are a source of tumor relapse." (PMID 25229616, 2014). "Thus, our findings strongly support the contention that HA/CD44-regulated c-Jun and miR-21 form a functional signaling axis that regulates tumor cell survival and Doxorubicin chemoresistance in triple negative breast cancer cells such as MDA-MB-468 cells." (PMID 24606718, 2014). "Specifically, it modulates CD44 alternative splicing, favoring the conversion from variant isoforms (CD44v) to the standard isoform (CD44s), which drives epithelial-mesenchymal transition (EMT) and enhances invasion and metastasis in triple-negative breast cancer." (PMID 40784984, 2025). "Sphere culture significantly enriched the subpopulation of CD44+/CD24−/low/EpCAM+ cells, supporting the hypothesis that CD44+/CD24−/low/EpCAM+ cells are a more selective cancer stem cell subpopulation than CD44+/CD24−/low cells in triple-negative breast cancer." (PMID 25229616, 2014).